MPO (myeloperoxidase)
Diseases named in the same sentence as MPO in open-access papers (continued):
Sharing a sentence is not in itself a finding about the gene and the disease.
viral infection (continued). "Upon bacterial and viral infection or following stimulation of neutrophils with eCIRP and cytokines/chemokines, they produce neutrophil extracellular traps (NETs), which contain chromatin decorated with citrullinated histone H3 (citH3), myeloperoxidase (MPO), and anti-microbial peptides." (PMID 35003095, 2021). "Moreover, we also evaluated whether MPO activity was altered in the liver by viral infection as an indirect index of neutrophil activation." (PMID 31653913, 2019). "The levels of MPO-DNA complexes were increased in the serum and BALF following viral infection but decreased after the administration of C-176." (PMID 40666504, 2025). "Neutrophil activation derived autoantigens (MPO, PRTN3, and PADI4) were prominently increased in blood of both SARS-CoV-1 and SARS-CoV-2 viral infections, while TSHR and PTPRN2 autoantigens were specifically increased in SARS-CoV-2." (PMID 34276672, 2021). "Infection with bacteria correlated with MPO, protozoa with CRP, AGP and Ferritin, while viral infection with CRP." (PMID 31442248, 2019). "After viral infection, the fold changes of FGT and TATc in BAL-fluid showed a significant correlation with ECP and MPO, while TATc also correlated with IL-8 in BAL-fluid." (PMID 24502801, 2014). "However, an unnoticed mild viral infection might induce priming (TNF-alfa) of neutrophils and translocation of PR3 and MPO to the cell surface." (PMID 16207324, 2005).
chronic obstructive pulmonary disease (19 papers, 2011 to 2025). A chronic and progressive lung disorder characterized by the loss of elasticity of the bronchial tree and the air sacs, destruction of the air sacs wall, thickening of the bronchial wall, and mucous accumulation in the bronchial tree. "NETs consist of the extracellular release of chromatin combined with histones, proteases, lactoferrin, cathepsins, and myeloperoxidase, and are associated with several chronic diseases, especially chronic obstructive pulmonary disease (COPD) and asthma." (PMID 41463036, 2025). "Myeloperoxidase has been implicated in the pathogenesis of chronic obstructive pulmonary disease (COPD)." (PMID 23637811, 2013). "For example, sample homogenization with DTT has been shown to reduce the concentration of sputum myeloperoxidase, a potential biomarker for chronic obstructive pulmonary disease." (PMID 38023718, 2023). "Pharmacological blockade of MPO activity also attenuated tissue injury and promoted resolution in murine models of pleurisy, immune complex vasculitis, and chronic obstructive pulmonary disease." (PMID 36421487, 2022). "In the lungs, MPO is used as a marker for systemic inflammation in smokers, and elevated MPO levels are observed in patients with chronic obstructive pulmonary disease." (PMID 36293108, 2022). "In addition, it relieved oxidative stress and inflammatory response via inhibition of the decrease in IL-6, IL-8, and myeloperoxidase (MPO), which provided support for its significance in chronic obstructive pulmonary disease in vivo." (PMID 36902097, 2023). "Components related to NETs, such as cf-DNA, MPO, NE, LL-37 and a-defensins have been found to be elevated in the airways of chronic obstructive pulmonary disease (COPD) patients, suggesting their possible involvement in airway inflammation and tissue damage." (PMID 38283037, 2023). "A double-blind randomized controlled trial investigated the effects of doxycycline on systemic inflammatory markers (cytokines and C-reactive protein) and neutrophil-specific markers, including MPO in the sputum of patients with stable chronic obstructive pulmonary disease (COPD)." (PMID 36421487, 2022).
endotoxemia (19 papers, 2014 to 2025). "In our work, chronic MeHg intoxication in adult mice caused systemic inflammation and endotoxemia, with increased circulating MPO levels." (PMID 36430321, 2022). "Interestingly, IKK inhibition in mouse endotoxemia resulted in a ~30% decrease in lung neutrophil-associated myeloperoxidase activity, whereas in CLP this treatment resulted in a complete abrogation of lung myeloperoxidase activity." (PMID 35634305, 2022). "In females, PDK4 overexpression primarily increased IL-6 expression and significantly elevated MPO levels during endotoxemia compared with WT females." (PMID 40626362, 2025). "Positive staining of MPO was highly observed in the lung of LPS-induced endotoxemia, but upon treatment with taVNS, there was a remarkable reduction in the strong expression of MPO of lung injury by LPS." (PMID 35203459, 2022). "The rate of MPO expression of the spleen in LPS-induced endotoxemia increased (four to five-fold) compared to the sham groups." (PMID 35203459, 2022). "In the murine endotoxemia model used during the present study, we observed accumulation of MPO-positive cells in the hearts of LPS-exposed mice." (PMID 33287422, 2020). "Similar patterns were observed for the relative expression of the neutrophil markers ELANE and MPO after the induction of endotoxemia, except in the spleen." (PMID 31817302, 2019). "AICAR or compound C treatment decreased ALT, AST, and TNF levels in serum, reduced CD68 expression and MPO activity in liver tissue of mice with endotoxemia." (PMID 24475189, 2014). "The authors found that endotoxemia-induced fibrinogen nitration was preceded by a stable increase in myeloperoxidase concentration in plasma." (PMID 24475207, 2014). "Endotoxemia caused an accumulation of CD45+ hematopoietic cells in the renal cortex, as determined by fluorescence intensity, which agrees with the MPO and NAG activities data and histopathological evaluation." (PMID 36615318, 2022). "Despite these limitations, our findings in a murine endotoxemia model demonstrate (i) the accumulation of MPO-positive cells in the mouse heart, (ii) aberrant cardiac FA utilization, and (iii) HOCl-mediated plasmalogen modification that gave rise to the formation of 2-ClHDA." (PMID 33287422, 2020). "During the present study, we tested whether endotoxemia increases MPO-dependent lipid oxidation/modification in the mouse heart." (PMID 33287422, 2020). "We used genetic and pharmacological approaches to investigate whether MPO induces aberrant lipid homeostasis at the BBB in a murine endotoxemia model." (PMID 32050431, 2020). "Correlations between plasma levels of MPO-DNA complexes and parameters of neutrophil activation and NET formation in an experimental human endotoxemia model." (PMID 33886636, 2021). "Increased levels of myeloperoxidase (MPO) and protein carbonyl groups and reduced production of sodium dismutase (SOD) were evident in mice with endotoxemia treated with VT 30 mL/kg compared with the other MV treatment groups and the nonventilated control mice." (PMID 32353952, 2020).
glioblastoma (19 papers, 2015 to 2025). The most malignant astrocytic tumor (WHO grade IV). "These analyses revealed cellular neighbourhoods associated with survival in patients with glioblastoma, which we leveraged to identify a unique population of myeloperoxidase (MPO)-positive macrophages associated with long-term survival." (PMID 36725935, 2023). "Finally, to further probe clinical relevance, we confirmed that increased levels of MPO+CD163−P2Y12−CD68+ macrophages were associated with prolonged survival using our balanced glioblastoma cohort." (PMID 36725935, 2023). "In addition, recent spatial analyses of human glioblastoma tumor samples identified regions of activated (myeloperoxidase) macrophages that are associated with improved clinical outcomes, suggesting anti-tumorigenic roles for certain macrophage populations in patients." (PMID 39052000, 2024). "Myeloperoxidase inhibition or Vps34 depletion resulted in reduced necrosis formation and prolonged mouse survival in an orthotopic glioblastoma mouse model." (PMID 38806658, 2024). "We identified a unique subset of neutrophil-like macrophages that stain positively for MPO, which appear to be beneficial for the survival of patients with glioblastoma." (PMID 36725935, 2023). "Consistently, recurrent glioblastomas contained fewer MPO+CD163−P2Y12−CD68+ macrophages compared with either STS or LTS tumours." (PMID 36725935, 2023). "We confirmed the presence of MPO+IBA1+ macrophages in glioblastoma tumours using immunofluorescence (IBA1 was used as an alternative macrophage marker to CD68 for validation purposes)." (PMID 36725935, 2023). "In a glioblastoma mouse model, neutrophils can transfer granules containing myeloperoxidase to tumor cells to induce lipid peroxide accumulation and ferroptosis in tumor cells, leading to tumor cell necrosis and glioblastoma progression." (PMID 38259464, 2023). "In glioblastoma, neutrophils transfer myeloperoxidase (MPO)-containing granules into tumor cells, and consequently facilitate iron-dependent aggregation of lipid peroxides inside tumor cells." (PMID 36514901, 2022). "Here, the authors show that in a xenograft mouse model of glioblastoma, tumour-infiltrating neutrophils amplify necrosis by promoting myeloperoxidase-induced tumour cell ferroptosis." (PMID 33110073, 2020). "The enhanced expression of MPO and citH3 demonstrated increased NETs secretion in the glioblastoma microenvironment." (PMID 32296583, 2020). "Notably, myeloperoxidase, a key component of NETs originating from neutrophil-specific granules, directly induces ferroptosis in glioblastoma cells." (PMID 38993565, 2024). "Furthermore, myeloperoxidase, a neutrophil-specific granule and the main component of NETs, can directly induce ferroptosis in glioblastoma cells." (PMID 37121969, 2023). "As the majority of MPO+ macrophages were CD163-P2Y12- and were associated with better survival, they chose the combination of MPO and IBA1 as the predictive algorithm for clinical outcomes in glioblastoma." (PMID 37156758, 2023). "In glioblastoma (GBM), TANs deliver MPO to tumor cells through cell membrane fusion or exosomes, stimulating a significant increase in lipid peroxidation markers such as MDA." (PMID 40535125, 2025). "The neutrophil-MPO-mediated ferroptosis of cancer cells in the hyperactivated transcriptional coactivator with PDZ-binding motif-driven mouse model of glioblastoma (GBM) involves the accumulation of iron (Fe2+)-dependent lipid peroxides." (PMID 37380989, 2023). "Using single-cell RNA-sequencing datasets from patients with glioblastoma, we identified genes enriched in MPO+ macrophages versus MPO− macrophages." (PMID 36725935, 2023). "To test the practicality of our findings using a lower-plex technology, we performed immunohistofluorescence co-staining for MPO and IBA1 to evaluate survival outcomes in a cohort of 135 patients with glioblastoma." (PMID 36725935, 2023).
glioblastoma (continued). "Neutrophil myeloperoxidase (MPO) induces tumor cell ferroptosis to create a tumor suppressive TIME for tumor growth and metastasis, including glioblastoma." (PMID 37380989, 2023). "Studies found that in glioblastoma (GBM), neutrophils transfer particles containing MPO to tumor cells, which induce accumulation of lipid peroxides and iron in tumor cells, and trigger ferroptosis of tumor cells." (PMID 35619718, 2022). "In the glioblastoma (GBM) model, neutrophils transfers myeloperoxidase particles into tumor cells, inducing iron-dependent accumulation of lipid peroxides in tumor cells and promoting iron-dependent necrosis of glioblastoma." (PMID 34630843, 2021). "The avidin-biotin peroxidase technique was used to detect various markers, such as CD3 (T-cells), CD8 (cytotoxic T-cells), CD68 (macrophages), myeloperoxidase (MPO), heat shock protein 70 (HSP70), and caspase-3, in glioblastoma tissues treated with NPs and radiotherapy." (PMID 40255989, 2025). "In glioblastoma, macrophage clusters enriched in LTS highly expressed MPO." (PMID 37156758, 2023).
idiopathic pulmonary fibrosis (19 papers, 2015 to 2026). Idiopathic pulmonary fibrosis (IPF) is a nonneoplastic pulmonary disease that is characterized by the formation of scar tissue within the lungs in the absence of any known cause. "Previous studies have shown that a usual interstitial pneumonia (UIP) pattern is the most prevalent pattern on high-resolution computed tomography (HRCT) in patients with MPO-ANCA-associated interstitial pneumonia." (PMID 31675941, 2019). "The most predominantly observed pattern is usual interstitial pneumonia (UIP), which is detected in up to 74.5% of cases and is more often associated with MPO-ANCA than PR3-ANCA." (PMID 40649005, 2025). "Clinical features compatible with MPA diagnosis develop in up to 25% MPO-ANCA-positive patients whose ILD was initially classified as idiopathic pulmonary fibrosis (IPF)." (PMID 38445024, 2024). "Furthermore, it has been documented that individuals who are MPO-ANCA-positive have a higher propensity to develop usual interstitial pneumonitis, bronchiectasis, alveolar hemorrhage, pleural effusion, lymph node enlargement, and pulmonary venous congestion." (PMID 40988257, 2025). "Additionally, the usual interstitial pneumonia (UIP) pattern is more common in MPO-ANCA-positive ILD cases, suggesting potential mechanistic overlap with IPF." (PMID 41007698, 2025). "In addition, in the in vivo study in idiopathic pulmonary fibrosis (IPF) rats, combined particles showed a 1.17 and 3.53-fold reduction in hydroxyproline content, whereas myeloperoxidase activity showed a positive effect against IPF." (PMID 36679199, 2023). "Patients initially diagnosed with idiopathic pulmonary fibrosis (IPF) may have positive ANCAs, particularly MPO-ANCAs, during the course of the disease, found in 8.5% of them at presentation, while after five years, 24.3% of them will eventually develop other features of MPA." (PMID 38791316, 2024).
lymphoma (19 papers, 2012 to 2025). A malignant (clonal) proliferation of B- lymphocytes or T- lymphocytes which involves the lymph nodes, bone marrow and/or extranodal sites. "It has been described in patients with granulomatous disease, myeloperoxidase deficiency, severe combined immunodeficiency, human immunodeficiency virus infection, organ transplantation and lymphoma." (PMID 25026870, 2014). "In both the WHO-HEM5 and the ICC classifications, these cases would typically be classified as B-lymphoblastic leukemia/lymphoma (B-ALL) with dim MPO expression." (PMID 40075717, 2025). "The risk of lymphoma varies with dietary intake of fruits and vegetables in the presence of particular SNPs, such as NOS1, NOS2A, MPO, and SOD3, with more significant results for NOS1." (PMID 37759977, 2023). "Specifically, staining for myeloperoxidase (MPO-expressed in 66% to 96% of MS) is used to help differentiate lesions from lymphoma." (PMID 35565314, 2022). "The successful treatment of eight GPA and two MPO patients with RTX with the lymphoma protocol lasting for a median of 33.5 months was also reported." (PMID 36552276, 2022). "Data obtained from this study showed that, especially in DLBCL and FL subtypes, the risk of lymphoma varies with dietary intake of fruits and vegetables in the presence of particular SNPs of some oxidative stress pathway genes, such as NOS1, NOS2A, MPO, and SOD3." (PMID 37759977, 2023). "Immunohistochemistry is indispensable in cases in which lymphoma and lupus lymphadenitis are histological differential diagnoses due to the presence of CD68 and MPO-positive histiocytes in KFD." (PMID 39439650, 2024). "Notably, in a preclinical model of lymphoma, Mpo mRNA was found to be expressed over 57‐fold higher in granulocytic MDSCs when compared with normal neutrophils isolated from tumour‐bearing or naive mice, respectively, suggesting that granulocytic MDSCs are a rich source of MPO in cancer." (PMID 37699574, 2023). "MPO is the marker with the highest sensitivity and specificity for IMS, with positive expression in 66% to 96% of patients, which can be distinguished from lymphoma." (PMID 36281103, 2022). "Neoplastic cells were positive for monocytic markers (MPO, Iba‐1) and negative for lymphoid markers (CD3, CD20, and CD79), excluding lymphoma as a differential diagnosis." (PMID 39289176, 2024). "MPO and PAX-5 staining revealed the lack of B cells, granulocytes, and monocytes in spleen lymphomas." (PMID 35852337, 2022). "Type of infiltrating cells (CD8+ T cells prevalence), absence of hematoxylin bodies, or myeloperoxidase co-expression by CD68 histiocytes in lymph node biopsies from patients with Kikuchi-Fujimoto can be helpful in differentiation between SLE and malignant lymphoma." (PMID 35024942, 2022). "B-lymphoblastic leukemia/lymphoma may express one or more markers of myeloid lineage, including CD13 and CD33, but is usually negative for moderate to high levels of myeloperoxidase expression (which can be assessed by flow cytometric analysis, cytochemical, or immunohistochemical staining)." (PMID 40227608, 2025).